HK2 (hexokinase 2)
Diseases named in the same sentence as HK2 in open-access papers (continued):
Sharing a sentence is not in itself a finding about the gene and the disease.
tumor (continued). "Glucose uptake by tumor cells is very high because tumor cells grow and proliferate very rapidly, and this process is accompanied by the production and accumulation of large amounts of lactic acid and the upregulation of the key regulatory factor HK2, in accordance with the Warburg effect." (PMID 36379920, 2022). "Besides the effect of tumor cell-derived lactic acid, enhanced endogenous aerobic glycolysis, also known for induction of pro-tumoral TAMs, was confirmed by a proteomic analysis illustrating the upregulation of HK2, phosphofructokinase, and ENO1 in TAMs." (PMID 36358644, 2022). "To determine whether 3-BP or/and doxorubicin could affect tumor cells mediated pericyte’s glycolytic change, we examined the effect of conditioned medium harvested from cancer cells pre-treated with 3-BP or/and doxorubicin on pericyte-HK2 and ROCK2 expression." (PMID 34650057, 2021). "Moreover, HK2 was recently found to be closely related to tumor progression." (PMID 34345220, 2021). "All above data indicated that HK2 might play a key role in tumor progression." (PMID 34345220, 2021). "In addition, GCK and HK2 expression tends to be inversely correlated in tumor samples." (PMID 33594203, 2021). "Additionally, HK2 plays an important role in tumor initiation and maintenance." (PMID 33867844, 2021). "Furthermore, a transcriptome sequencing analysis was performed in HK2-overexpressing monoclonal cell lines to screen for potential target genes and signal transduction pathways that are likely involved in HK2-mediated cell migration and tumor metastasis in cervical cancer." (PMID 34758823, 2021). "Additionally, QUE significantly decreased the level of HK2 and tumour growth in vivo." (PMID 32843908, 2020). "Moreover, HK2 is highly expressed in many tumor tissues and could be a potential target for antitumor therapy based on the promising results of preclinical studies." (PMID 33160373, 2020). "Thus, HK2 is a promising anti-tumor target for cancer treatment." (PMID 32424132, 2020). "Furthermore, TIGAR could also protect tumour cells against oxidative stress, while HK2 is crucial for energy production, preservation of mitochondrial integrity and cell survival." (PMID 32969187, 2020). "Furthermore, the deletion of HK2 synergized with sorafenib to reduce tumor growth." (PMID 32331347, 2020). "Moreover, the HK2 expression level was much higher in the recurrent GBM tumours." (PMID 32279420, 2020). "LncRNA-PVT1 via regulating miR-497/HK2 axis could promote glycolysis and tumor progression in OS." (PMID 33123468, 2020). "Moreover, a high HK2 level in tumor cells often indicates the enhanced glycolytic phenomenon." (PMID 32336952, 2020). "Additionally, both B7-H3 and HK2 expression increased with tumor stage." (PMID 30952834, 2019). "PD-L1 enhances glycolysis in NSCLC by upregulating HK2, which might dampen anti-tumor immunity." (PMID 31718692, 2019). "Despite of this limitation, our results regarding the relationship between PD-L1, HK2, and T-cell effector function suggests that combination analyses of HK2 and PD-L1 expression in tumor cells might provide useful information to predict the TME immune signature in NSCLC." (PMID 31718692, 2019). "Therefore, HK2 inhibitors or in vivo deletion by CRISPR/Cas9 could affect tumor cells by inhibiting tumor metabolism and promoting apoptosis." (PMID 31718692, 2019). "Moreover, other metabolically active tissues, including skeletal muscle, cardiac, and adipose tissues, also express HK2, indicating that the anti-tumor effects of HK2 inhibition may be challenged or limited by non-specificity and systemic toxicity." (PMID 31450721, 2019). "Similarly, the values of ECAR and OCR were decreased remarkably after HK2 silencing in tumor cells." (PMID 31655629, 2019). "Likewise, inhibiting HK2 ubiquitination mitigated tumor formation." (PMID 31201299, 2019). "Finally, HK2 silencing synergizes with sorafenib to inhibit tumor growth." (PMID 29386513, 2018).
tumor (continued). "In addition, HK1 knockdown induced the EMT phenotype and accelerated tumor malignancy; in contrast, HK2 silencing did not cause any morphological change and did not affect cancer cell growth and migration." (PMID 29721175, 2018). "Moreover, HK2 silencing also synergized with sorafenib to inhibit tumor growth in mice." (PMID 30524660, 2018). "Importantly, HK2 silencing synergized with metformin to inhibit tumor growth of human HCC cells." (PMID 29386513, 2018). "The two drugs effectively controlled the tumor growth by blocking the β2-AR, and then consequently suppressing the expression of p-Akt, p-mTOR, Bcl-2, cyclin D1, HK2 and GLUT1, which indicated that propranolol could enhance the efficacy of vemurafenib, a member of TKIs." (PMID 29416656, 2018). "Finally, HK2 deficiency markedly increased the susceptibility to cell death induced by the FDA-approved drug sorafenib and markedly increased sorafenib inhibition of tumor growth in vivo." (PMID 29386513, 2018). "Xenografts with both miR-125a and HK2 overexpression exhibited reduced cell mitosis and increased cell apoptosis compared to xenografts with HK2 overexpression, suggesting that miR-125a overexpression could attenuate the tumor-promoting effect of HK2." (PMID 28596599, 2017). "Therefore, elevated expression of HK2 is critical for promoting tumor progression." (PMID 27824926, 2016). "The fact that hK2 is a secreted antigen could therefore potentially increase its availability for targeting and, in combination with the high affinity of 177Lu-m11B6, lead to better tumor penetration." (PMID 26983637, 2016). "Moreover, we demonstrated that resveratrol downregulates the expression of HK2, a key regulator of tumor glycolysis, which could result in metabolic stress associated apoptosis." (PMID 25938543, 2015). "Knockdown of PKM2 not only suppressed tumor growth in the livers but also suppressed the growth of metastatic lesions found in the lungs as shown by the Xenogen imaging and expression of human genes HK2 in the mouse lung tissues (5/5 mice in NTC vs 3/5 mice in shPKM2)." (PMID 25541689, 2014). "We therefore hypothesized that if HK2 endowed tumor cells with a proliferative advantage and apoptotic resistance in response to EBV-encoded LMP1, knocking down the expression of HK2 might decrease glycolysis and survival advantage in LMP1-overexpressing cells." (PMID 24662831, 2014). "PHDs reduced HK-2 expression to 43.7% in 4T1 cells and 42.1% in CT26 cells, which consequently impaired glycolysis in tumor cells." (PMID 41924308, 2026). "Systemically administered drugs typically accumulate in the liver, and since HK2 is predominantly expressed in HCC, even modest doses of HK2 inhibitors can specifically target tumor cells with minimal impact on normal liver cells." (PMID 40818043, 2026). "ADX markedly reduced intratumoral DHT and downregulated glycolytic genes (HK2, PFK2, and LDHA) and secretory proteins expressed by the tumor, including stanniocalcin 2, potentially mediating paracrine effects in the sclerotic bone response." (PMID 42149634, 2026). "In this review, we summarize how key glycolytic regulators, including GLUT1, HK2, PFKFB3, PDK1, and LDHA, are controlled by oncogenic, microenvironmental, and non-coding RNA-mediated pathways to reshape tumor metabolism." (PMID 42317327, 2026). "For example, in pancreatic cancer, inhibiting the expression of NR3C2 leads to the upregulation of glycolytic enzymes HK1, HK2, and LDHA, promotes glucose uptake and lactate production and accelerates tumor growth." (PMID 41219936, 2025). "Following tumor-specific Cat-B cleavage, NanoTAC induces potent pyroptosis through PDT integrated with HK2 proteolysis, leading to complete regression of refractory TNBC and suppression of recurrence and metastasis." (PMID 40998785, 2025).
tumor (continued). "Regarding glycolytic enzymes, inhibiting key enzymes in the glycolytic pathway, such as hexokinase 2 (HK2) or pyruvate kinase M2 (PKM2), can reduce the glycolytic flux and limit the availability of metabolic intermediates necessary for tumor survival." (PMID 40710528, 2025). "In the hypoxic TME, stabilization of HIF-1α not only enhances glycolytic flux through the upregulation of HK2 and PDPK1, but also supports tumor cell motility and invasiveness." (PMID 41450919, 2025). "Meanwhile, STING not only participates in the immune response but also acts as a cell‐intrinsic metabolic checkpoint to limit aerobic glycolysis by targeting hexokinase 2 (HK2), thereby promoting anti‐tumor immunity in vivo." (PMID 40448435, 2025). "Enzymes, such as Hexokinase 2 (HK2), Pyruvate Kinase M2 (PKM2), and LDH, are regulates in tumours to accelerate glycolysis and lactate production." (PMID 40175681, 2025). "Mammals express four hexokinase (HK) isoforms (HK1, HK2, HK3, and HK4), among which HK2 is markedly upregulated in tumor tissues compared to normal counterparts." (PMID 40756987, 2025). "By targeting enzymes such as LDHA, GLUT1, HK2, PKM2, GLS1/2, FASN, ACLY and ACC, researchers have demonstrated the feasibility of disrupting tumor bioenergetics and biosynthetic machinery." (PMID 40941984, 2025). "Epigenetically, PRL-3 promotes primary tumor proliferation and metastatic capacity by upregulating PKM2 and glycolytic enzymes such as Glut1, HK2, and LDHA, collectively enhancing glucose uptake and lactate production." (PMID 40842995, 2025). "miR-155 upregulates HK2 and monocarboxylate transporter 4 (MCT4), thereby increasing glycolytic activity and promoting rapid tumor growth." (PMID 40303296, 2025). "MYC regulates genes involved in glucose uptake (GLUT1) and glycolysis (HK2, PFK1), enhancing the glycolytic capacity of tumor cells." (PMID 41281744, 2025). "Preclinical studies report that HK2 inhibition not only impairs tumor growth but also enhances TAM polarization toward the M1 phenotype, boosting anti-tumor immunity." (PMID 40433363, 2025). "This review discusses how epigenetic mechanisms, including m6A methylation and ceRNA networks involving circRNAs and microRNAs, modulate key glycolytic enzymes such as PKM2, HK2, and PGK1, thereby promoting tumor growth, metastasis, and chemoresistance." (PMID 40977684, 2025). "Clinically relevant glycolytic markers including HK2 and LDHA demonstrate strong correlations with advanced tumor stage, chemotherapy failure, and poor prognosis." (PMID 40977684, 2025). "Mechanistically, glucose metabolic dominance triggers NSUN2 upregulation in tumor cells, where this functional RNA methyltransferase stabilizes key glycolytic transcripts (GLUT1, HK2, PFKM) through mRNA methylation." (PMID 40765828, 2025). "Western blot showed that emodin downregulated the protein levels of HK2, PKM2 and LDHA in the nude mice, indicating that emodin inhibited glycolysis in the tumor of the nude mice." (PMID 41426311, 2025). "The expression of glycolytic genes HK2, GAPDH and ENO1 were analysed in the context of MYCN amplification, INSS tumour stage progression and overall event free survival using KM plots." (PMID 41420301, 2025). "Aspirin inhibits tumor growth by activating the AMPK/SIRT3/HK-II pathway, leading to hexokinase 2 (HK-II) dissociation from mitochondria, impaired glycolysis, and mitochondrial dysfunction." (PMID 40710178, 2025). "HIF-1α plays a pivotal role in tumor metabolism by promoting glycolysis through the upregulation of GLUT1, HK2, and LDHA." (PMID 41281744, 2025).
tumor (continued). "Using such approaches, researchers have detected the upregulated expression of various key glycolytic enzymes, such as hexokinase 2 (HK2), phosphoglycerate kinase 1 (PGK1), aldolase, and lactate dehydrogenase A (LDHA), in multiple tumor cell types." (PMID 40313939, 2025). "Increased glycolysis in cancer cells is driven by elevated expression of key enzymes like HK2 and PKM2, with HK2 promoting tumor glycolysis and metastasis." (PMID 41331197, 2025). "When TIA1 was silenced, BCG lost its efficacy: Sh-mTia1 tumors retained intense photon flux, persistent tumor architecture, high LDHA/HK2/PKM2 levels, and unaltered lactate output." (PMID 41300366, 2025). "In liver cancer models, curcumin reduces HK2 expression by inhibiting the activity of CSN5 kinase, which decreases glycolytic flux and invasive capacity, effectively prolonging the survival of tumor-bearing animals." (PMID 41515171, 2025). "A glucose metabolism advantage drives NSUN2 upregulation in tumor cells, which stabilizes key glycolytic gene transcripts (GLUT1, HK2, PFKM) via mRNA methylation, enhancing tumor cells’ competitive advantage in glucose uptake." (PMID 41256859, 2025). "Together with statistical analysis of necrotic tumor areas, these findings indicated that 2-DG inhibited tumor growth by activating cAMP/PKA pathway, thereby suppressing HK2 expression and promoting GSDME-mediated pyroptosis." (PMID 41415273, 2025). "Our study demonstrated that reducing SLC7A5 expression significantly decreased HK2, LDHA, Glut1, and PDK1 levels in HGC27R cells, MKN45R cells, and tumor tissues." (PMID 40133832, 2025). "Mechanistically, lncRNA-SLCC1 forms a complex with AHR to transcriptionally activate the glycolysis-promoting enzyme HK2, thereby driving glycolytic metabolism and accelerating CRC tumor growth." (PMID 41361062, 2025). "A cadre of tumor-suppressive miRNAs—miR-3662, miR-199a-5p, miR-125a, miR-885-5p counter this shift by directly targeting HIF1A or the rate-limiting enzyme Hexokinase 2 (HK2)." (PMID 41007803, 2025). "The inhibition of hexokinase 2 (HK2) decreases the number of MDSCs and enhances the efficacy of the ant-PD-L1 antibody in a tumor mouse model." (PMID 40710359, 2025). "Building on the rationale that key glycolytic enzymes, such as HK2, LDHA, and PKM2, are central drivers of both tumor metabolism and the radioresistant TME, the following section focuses on therapeutic strategies directly targeting these molecules." (PMID 41441035, 2025). "HK2 expression is significantly elevated in most HCC cell lines and tumor tissues compared to normal cell lines and tissues." (PMID 41246345, 2025). "Other compounds targeting key glycolytic enzymes (such as 2-deoxyglucose and 3-bromopyruvate, which are HK2 inhibitors, and PKM2-IN-1, a PKM2 inhibitor) have shown anti-tumor effects in preclinical models." (PMID 40658684, 2025). "TNF-α enhances glycolysis and lactate production in tumor cells via the NF-κB signaling pathway, promoting the expression of GLUT1 and hexokinase 2 (HK2), and thereby facilitating tumor progression." (PMID 41216196, 2025). "For example, TAMs secrete cytokines such as IL-6 and TNF-α, which upregulate glycolytic enzymes like HK2 and LDHA in tumor cells, amplifying lactate production and fostering a pro-tumorigenic environment." (PMID 41007256, 2025). "HK2 is the most well-characterized isoform of the HK family and is significantly overexpressed in GBM tumor cells compared to adjacent normal tissues, correlating with GBM prognosis." (PMID 39877360, 2024). "This self‐amplifying circuit relied on the accumulation of the ChREBP activator G6P due to the upregulation of the oncogenic enzyme hexokinase 2 (HK2), responsible for G6P synthesis in tumor cells." (PMID 38837736, 2024). "In mice, HK2 depletion inhibits glycolysis and induces OXPHOS, enhancing the sensitivity of HCC to systemic drugs, such as sorafenib, thereby inhibiting tumor growth." (PMID 38424041, 2024).
tumor (continued). "Within the glycolysis pathway, genes such as HK2, PFKP, and PKM displayed elevated expression, thereby emerging as prospective targets warranting exploration for restraining tumor cell glycolytic activity." (PMID 38414015, 2024). "Specifically, the activation of this pathway influences the activities of key enzymes such as HK2, ATP-citrate lyase (ACL), and the stabilization of hypoxia-inducible factor 1-alpha (HIF1a), ultimately enabling the tumor cells to meet their energy needs." (PMID 38479191, 2024). "Hypoxia has been found to enhance lactate production and tumor growth through activation of HIF1-α, GLUT1, HK2, PKM2, PDK, ENO1 or LDHA." (PMID 38233839, 2024). "Hexokinase 2 (HK2), a glycolytic enzyme that catalyzes the first step of glucose metabolism, can be significantly induced in tumor cells through a variety of mechanisms." (PMID 38565547, 2024). "Curcumin inhibits the glycolytic activity of tumor cells by inhibiting the expression and activity of HK2 in HCT116 and HT29 cells, and induces the dissociation of mitochondrial HK2 through AKT phosphorylation, leading to mitochondria-mediated apoptosis." (PMID 39330497, 2024). "α-Hederin have been found to significantly regulate tumor metabolism, by inhibiting glycolysis and the expression of GLUT1, HK2, PKM2 and LDHA." (PMID 38362150, 2024). "Recently, it was discovered that AhR binds to lncRNA and actively controls the expression of the glycolytic enzyme gene hexokinase 2 (HK2), stimulating glycolytic metabolism and accelerating tumor growth." (PMID 38434684, 2024). "Identification based on the HK subtype showed that most of the non-tumor tissues expressed only HK1, while most of the tumor tissues expressed both HK1 and HK2." (PMID 38581001, 2024). "In hypoxia, the expression of the glycolytic genes PKM2 (pyruvate kinase M2), HK2 (hexokinase 2), and LDHA (lactate dehydrogenase A) is upregulated, which promotes glycolysis in tumor cells." (PMID 38491378, 2024). "For instance, sulforaphane demonstrates anti-tumor properties by regulating several signaling pathways, such as Nrf2/Keap1, AKT1/HK2, and NF-κB/MMP-9." (PMID 38612546, 2024). "CCL5 and CCL18 upregulate various glycolysis-promoting factors, including hexokinase 2 (HK2), phosphoglycerate kinase 1 (PGK1), glucose-6-phosphate dehydrogenase (G6PD), and pyruvate kinase, further facilitating tumor progression." (PMID 38714539, 2024). "In gastric cancer, c-Myc collaborates with HIF-1α, a key protein in activating AEG, to enhance the expression of glycolytic enzymes like Glucose Transporters (GLUT), HK2, PFK, PGK, and LDHA, significantly elevating AEG levels in tumor cells." (PMID 39906672, 2024). "IHC showed that 5-HT treatment upregulated HK2 and HIF-1α expression in tumor tissues, which was reversed by PI3K inhibitor treatment." (PMID 39385213, 2024). "HK2 and LDHA mRNA expression levels were upregulated in OS tumor tissues, and their expression levels were negatively correlated with miR-577 expression." (PMID 38218855, 2024). "Downregulation of the expression levels of HK2, PFKP, and PDH, as well as the phosphorylation level of ERK1/2 was observed in both 2D and 3D cultures or tumor tissues in nude mouse xenograft models treated with the combination of two agents." (PMID 39770959, 2024). "In this project, MYO16-AS1 was found to inhibit HK2 mRNA degradation through competitive binding with IGF2BP3 protein in the cytoplasm, inhibiting tumor progression both in vitro and in vivo." (PMID 38041756, 2024). "HK2 and PKM2, the predominant isoforms of pyruvate kinase and hexokinase, respectively, are upregulated in tumor cells." (PMID 38933335, 2024). "SESN2 disrupts the stability of hexokinase 2 (HK2) mRNA by inhibiting the formation of HK2 mRNA-based LLPS droplets, thereby reshaping tumor metabolism." (PMID 38247494, 2024).